MELK (maternal embryonic leucine zipper kinase)
Diseases named in the same sentence as MELK in open-access papers (continued):
Sharing a sentence is not in itself a finding about the gene and the disease.
cancer (continued). "MELK and FAK are involved in cell proliferation, survival, and migration, making them critical players in cancer metastasis and resistance to therapies." (PMID 37925403, 2023). "Studies by Giuliano and colleagues and Lin and colleagues showed that MELK deletion by CRISPR/Cas9 in CAL-51 and MDA-MB-231 TNBC cells had little effect on the proliferation of these cancer cells." (PMID 37377604, 2023). "Based on the statistical analyses of the PPI network of upregulated genes, AURKA, AURKB, TTK, MELK, and KIF20A were also involved in module 1, indicating their importance both in primary tumorigenesis and cancer progression." (PMID 37231064, 2023). "Maternal embryonic leucine-zipper kinase (MELK) regulates cell cycle progression and is highly expressed in many cancers." (PMID 35749404, 2022). "It is significantly overexpressed in many cancers, such as CRC, lung cancer, and liver cancer, while MELK silencing slows or inhibits the growth, invasion, stemness, and tumorigenicity of these cancers and other cancer cell lines." (PMID 35440604, 2022). "Maternal embryonic leucine zipper kinase (MELK) is an AMPK serine/threonine kinase and has been proposed as a potential therapeutic target in several cancers." (PMID 35511171, 2022). "These 8 genes (SPP1, TTK, MELK, FOXM1, LYN, ARRB2, COL6A3, and CCL21) were further validated in more numbers of cancer tissue samples by quantitative real-time PCR (qRT-PCR)." (PMID 33829064, 2021). "MELK is a member of AMPK/Snf1 family of serine/threonine kinases, and the MELK protein expression is highly specific to proliferating cancer stem cells." (PMID 33801837, 2021). "MELK is considered as key member of AMPK family, and a therapeutic target for multiple type of cancers." (PMID 34588861, 2021). "The interactive analysis tool was applied to confirm the expression level of the eight DEGs (SPP1, TTK, MELK, FOXM1, LYN, ARRB2, COL6A3, and CCL21) in cancer and normal tissues." (PMID 33829064, 2021). "For the six cancer types (BRCA, KIRC, LUAD, LUSC, PRAD, and THCA) containing >50 normal samples, BUB1B, KIF4A, and MELK were among the 30 with the most significantly upregulated local entropy of four cancer types." (PMID 34097054, 2021). "In summary, this study demonstrated that MELK was highly expressed in ESCC and played an important role in regulating cancer development and progression." (PMID 32047721, 2020). "The invalidation of the published roles for MELK, SMYD2 and SMYD3 suggest that a much higher bar must be set for the use of genetic tools in cancer biology." (PMID 29856759, 2018). "Our pre-clinical data suggest that MELK is an attractive therapeutic target in MYCN- and MYC-driven cancers, such as NB." (PMID 29416794, 2018). "To unambiguously demonstrate that MELK is dispensable for the proliferation of certain cancer cell lines, we used CRISPR to generate clonal cell lines that lack MELK protein." (PMID 28337968, 2017). "It is also notable that TOPK, MELK, and FOXM1 were suggested as cancer stem cell markers and listed in top 30 of the “consensus stemness ranking (CSR) signature” genes." (PMID 26933922, 2016). "Maternal embryonic leucine zipper kinase (MELK) is upregulated in a variety of human tumors, and is considered an attractive molecular target for cancer treatment." (PMID 26701722, 2016). "Thus, MELK could also be a potentially important prognosis marker for some types of cancers." (PMID 24167714, 2013). "Maternal embryonic leucine-zipper kinase (MELK) is a serine/threonine kinase and is abundantly expressed in GBM and various other cancers." (PMID 23404835, 2013).
cancer (continued). "The protein kinase MELK is also abundantly expressed in various cancers including GBM and plays a pivotal role in survival of cancer cells and cancer stem cells." (PMID 23404835, 2013). "Thus, targeting MELK could be an effective strategy to treat multiple types of human cancer." (PMID 23283305, 2012). "We also investigated the biological characteristics of PSMA1 in cancer cells, and found that PSMA1 was stabilized by the phosphorylation in MELK overexpressing cells and that coexistence of PSMA1 and MELK enhanced the formation of mammosphere." (PMID 23283305, 2012). "Notably, MELK can bind to and phosphorylate EZH2 to elevate EZH2 expression, thus affecting medulloblastoma cancer stem‐like cell proliferation." (PMID 38652219, 2024). "The first were tightly regulated, through MELK, BRCA2, KIF14, BUB1, and TOP2A, by five TFs (NFE2L3, RUNX1, RUNX2, BHLHE40, and the aging cancer-specific SOX11), two LncRNAs (ST7OT1 and CDKN2BAS), and four miRNAs (miR-21-5p, miR-363-3p, miR-873-5p, and miR-138-1-3p)." (PMID 37191407, 2023). "On the other hand, in a CRISPR/Cas9 screen, deletion of MELK did not affect the cancer cells, calling into question its essentiality in cancer induction and cancer cells survival." (PMID 37175795, 2023). "While MELK’s role in embryogenesis and cancer was extensively studied, no thought was given to its role in normal skin cells and the possibility of using this kinase as a therapeutic stimulator for accelerated wound healing." (PMID 37175795, 2023). "Interestingly, among these factors, MELK has also been revealed in previous studies to activate the mTORC1 and mTORC2/AKT signaling pathways and promote cancer progression when expressed at high levels." (PMID 35440604, 2022). "MELK is a fascinating cell cycle-dependent protein kinase belonging to the sucrose non-fermenting 1 (Snf1)/adenosine monophosphate-activated kinase (AMPK) family and is highly expressed in most malignant tumors." (PMID 36523974, 2022). "We showed that fostamatinib (which can target PLK1 and other over-expressed serine/threonine kinases such as AURKA, MELK, NEK2, and TTK) is more active against cancer lines with more pronounced signatures of invasion (e.g., extracellular matrix organization/degradation)." (PMID 34680307, 2021). "Maternal embryonic leucine zipper kinase (MELK) is a serine/threonine protein kinase that is aberrantly expressed in many tumor types and demonstrated to be important for the formation and maintenance of cancer stem cells." (PMID 33658483, 2021). "On the strength of these results, we considered that MELK expression might benefit in OSCC development, particularly in the metastatic characteristic to cancer stem cells." (PMID 33962400, 2021). "Together, our results demonstrate that inhibition of HDAC4 activity impairs the proliferation of cells that overexpress MELK more than cells that do not overexpress MELK, thus revealing a potential targetable vulnerability of cancers that overexpress MELK." (PMID 34550356, 2021). "Previous studies demonstrated that MELK interacts with and phosphorylates its downstream substrates including FOXM1, eukaryotic translation initiation factor 4B (eIF4B) and SQSTM1, and thus promotes the malignant phenotype of human cancer." (PMID 32047721, 2020). "It is likely that MELK is required for cell proliferation in NB but is not essential in some of other cancer types." (PMID 29416794, 2018). "The MELK inhibitor used in this study, OTS167, is currently being tested in oncology clinical trials and has been shown to be effective in xenograft models of several cancer types." (PMID 29437778, 2018).
cancer (continued). "Our in vitro and in vivo experiments failed to reveal any cancer-related phenotypes affected by either the deletion or over-expression of MELK." (PMID 29417930, 2018). "For example, a recent study employing CRISPR pooled screening showed that the maternal embryonic leucine zipper kinase (MELK) is not involved in cancer cell line proliferation, in stark contrast to a large number of previous studies." (PMID 29856759, 2018). "In this current manuscript, we report that combining CRISPR and a small-molecule inhibitor in a variety of assays failed to reveal a role for MELK in several cancer-related processes." (PMID 29417930, 2018). "Here, we generate several additional knockout clones of MELK and demonstrate that across cancer types, cells lacking MELK exhibit wild-type growth in vitro, under environmental stress, in the presence of cytotoxic chemotherapies, and in vivo." (PMID 29417930, 2018). "We previously reported MELK as a promising therapeutic target and developed a potent MELK kinase inhibitor, OTS167, which showed strong antitumor effects in mice xenograft models of several cancer types." (PMID 28938528, 2017). "If MELK is not a cancer cell dependency, then drugs that inhibit MELK must either be ineffective at stopping cancer cell division or they must also act on other cellular targets." (PMID 28337968, 2017). "Nonetheless, our data suggest that specific MELK inhibitors are unlikely to be useful monoagents in cancer therapy." (PMID 28337968, 2017). "This did not stop cancer cells from multiplying, suggesting that MELK is not actually a cancer addiction." (PMID 28337968, 2017). "The results of this study suggest that any potential dependence on MELK in cancer is not easily modeled using common cell culture conditions." (PMID 28926338, 2017). "The results suggest that OTSSP167 may have additional mechanisms of action for cancer cell killing and caution the use of OTSSP167 as a MELK specific kinase inhibitor in biochemical and cellular assays." (PMID 27082996, 2016). "Of the 104 cases that had adjacent noncancerous mucosa present in the same section, MELK was expressed more frequently in the cancer lesion than the corresponding noncancerous mucosa (68.3% vs. 28.8%, p=0.036)." (PMID 26701722, 2016). "Given that our previous observation that the D150 residue of MELK is required for the interaction of MELK protein with the oncogenic transcriptional factors c-JUN and FOXM1 in a cancer-specific manner, it is likely that the kinase domain is essential for MELK-driven GSC survival." (PMID 24739874, 2014). "Given that mutations in the kinase domain or in other molecular elements of MELK do not appear to be a frequent event in cancers, the distinct function of MELK in normal and oncogenic stem cells is likely to be epigenetic." (PMID 24739874, 2014). "MELK (maternal embryonic leucine zipper kinase), which is a member of the AMPK (AMP-activated protein kinase)-related kinase family, plays important roles in diverse cellular processes and has become a promising drug target for certain cancers." (PMID 23922895, 2013). "MELK is important in oncogenesis as first emphasized in a previous finding, in which MELK expression is increased in tumor-derived progenitor cells and in cancers of non-differentiated cells." (PMID 24185907, 2013). "The experiment using the MELK-negative cancer cells supported the MELK-dependent growth suppressive effect of OTSSP167 on cancer cells." (PMID 23283305, 2012).
cancer (continued). "However, the downstream regulatory mechanisms through which MELK affects RFA efficacy and residual cancer progression remain unknown." (PMID 39871325, 2025). "Furthermore, CRISPR/Cas9 mediated knockout or interference demonstrated that MELK is not essential for proliferation of the mass of cancer cells under many tested conditions." (PMID 39355119, 2024). "Moreover, as most of the studies of MELK were carried out in cancer cells, embryonic cells, and following genetic knockout in a mouse organism, our study sheds new light on the role of MELK in healthy, non-transformed somatic cells in cell culture." (PMID 37175795, 2023). "In addition, multiple high-throughput genetic screens in multiple cell lines, including TNBC cell lines, did not identify MELK as a potential cancer target." (PMID 37377604, 2023). "In addition, FOXM1B/C have been demonstrated to promote cancer progression through the interaction with other proteins, such as β‐catenin, STAT3, SMAD3, HSP70, nucleophosmin (NPM), maternal embryonic leucine‐zipper kinase (MELK), and Pin1." (PMID 33314660, 2021). "In this regard, McDonald IM and Graves LM mentioned in their review the possibility that MELK is functionally redundant for a specific cell cycle pathway, such that MELK is not indispensable for the cell cycle in normal cells but is necessary for specific conditions in cancer cells." (PMID 34285339, 2021). "As we observed no role for MELK as either an oncogene or a cancer dependency, we sought to instead investigate whether its cell cycle-dependent expression pattern could explain its prognostic value." (PMID 29417930, 2018). "We therefore considered the possibility that, rather than functioning as an oncogene or a cancer dependency, MELK expression could report cell division within a tumor." (PMID 29417930, 2018). "To investigate the role of MELK in cancer-related processes beyond cell proliferation, and to assess the therapeutic potential of immediate MELK inhibition, we performed assays combining CRISPR-knockout cell lines with a recently described, highly specific MELK inhibitor." (PMID 29417930, 2018). "Thus, while we do not consider results from large-scale screens to be dispositive, we believe that these findings, coupled with our own experimental evidence, suggest that MELK expression is not required for cancer cell proliferation." (PMID 28337968, 2017). "With the current data, we cannot rule out the possibility that MELK may play a crucial role for cancer maintenance in vivo, which would only manifest in more context-dependent assays." (PMID 28926338, 2017). "In total, this data suggests that MELK is not a common cancer dependency." (PMID 28337968, 2017). "Moreover, MELK expression levels were strongly correlated with those of forkhead box protein M1 (FOXM1) known as an important transcriptional factor and a master regulator of mitosis in cancer stem cells." (PMID 26933922, 2016). "First, it is not clear whether the MELK/FOXM1 protein complex plays a positive role in cancers or cancer stem cells in other organs." (PMID 23404835, 2013). "Since membrane ruffling is related to tumor cell mobility and cancer metastasis, we performed Matrigel invasion assay and observed significantly higher invasiveness of the cells overexpressing both DBNL and MELK than the control cells or those overexpressing either of the two genes." (PMID 23283305, 2012). "The inconsistency between the expression level and the expected prognosis in the other five genes (RHPN1-AS1, MELK, EIF5AL1, and G6PC3: upregulated, but HR < 1; NLGN2: downregulated, but HR > 1) may be attributed to a protective response mechanism in order to resist the development of cancer." (PMID 32953881, 2020).
cancer (continued). "However, we could not find any possible candidate factors involved in the MELK-TOPK-FOXM1 pathway in any deposited cancer database." (PMID 26933922, 2016). "Then, the DFS was further analyzed and higher expression of MELK indicated poor prognosis in HCC, while no statistical significance of MELK for predicting prognosis of patients in other cancer types was observed." (PMID 35693941, 2022). "The inactivation of MELK via CRISPR remains sensitive to OTS167 and does not affect the potency of cancer-derived cell lines." (PMID 33748164, 2021). "In all experiments conducted thus far, no phenotypes have been observed only in MELK-WT cells after HTH-01–091 treatment, further verifying that MELK is dispensable for cancer cell growth." (PMID 29417930, 2018). "High MELK expression correlates with worse overall survival, recurrence-free survival, and distant metastasis-free survival, aligning with previous studies that have identified MELK as a negative prognostic factor in TNBC and other cancers." (PMID 40076867, 2025). "Furthermore, it has been found that MELK suppression by siRNA did not recapitulate the mitotic effects of OTSSP167 treatment in MCF7 and Hela cancer cell lines." (PMID 31861475, 2019). "The reexpression of MELK in TNBC, as opposed to normal tissues, is hypothesized to be driven by these genetic changes that reactivate embryonic pathways involved in cell cycle regulation and survival, crucial for cancer cell proliferation and resistance to apoptosis." (PMID 40076867, 2025).